FDPS (farnesyl diphosphate synthase)
Description:
Key enzyme in isoprenoid biosynthesis which catalyzes the formation of farnesyl diphosphate (FPP), a precursor for several classes of essential metabolites including sterols, dolichols, carotenoids, and ubiquinones. FPP also serves as substrate for protein farnesylation and geranylgeranylation. Catalyzes the sequential condensation of isopentenyl pyrophosphate with the allylic pyrophosphates, dimethylallyl pyrophosphate, and then with the resultant geranylpyrophosphate to the ultimate product farnesyl pyrophosphate.
Synonyms: FPS; FPPS; POROK9
Tractability: Small molecule: an approved drug acts on it; a structure with a bound ligand is known; a high-quality ligand is known; it has a high-quality binding pocket; it belongs to a druggable protein family. PROTAC: ubiquitination databases record sites on it; its protein half-life has been measured; a small molecule that binds it is known.
Target class: Enzyme; Transferase
Chemical probes: MINODRONIC ACID, RISEDRONIC ACID, ZOLEDRONIC ACID (high quality)
Safety:
Unwanted effects reported when the protein is acted on. In parentheses: how it was acted on, where the effect was seen, and who reports it.
osteonecrosis (source: ClinPGx)
Gene: Protein-coding gene on chromosome 1 (155,304,786 to 155,320,666, forward strand). Ensembl gene ENSG00000160752.
Subcellular location: Cytoplasm
Subcellular location (Human Protein Atlas): Cytosol; Nucleoplasm
Pathways (Reactome):
Metabolism: Activation of gene expression by SREBF (SREBP); Lanosterol biosynthesis
Gene Ontology:
Molecular function: (2E,6E)-farnesyl diphosphate synthase activity; dimethylallyltranstransferase activity; protein binding; RNA binding; prenyltransferase activity; transferase activity, transferring alkyl or aryl (other than methyl) groups
Biological process: cholesterol biosynthetic process; farnesyl diphosphate biosynthetic process; farnesyl diphosphate biosynthetic process, mevalonate pathway; geranyl diphosphate biosynthetic process; geranylgeranyl diphosphate biosynthetic process; isoprenoid biosynthetic process; zymosterol biosynthetic process
Cellular component: cytoplasm; cytosol
Genetic constraint (gnomAD): Loss-of-function variants: 28 observed, 51.57 expected, observed/expected ratio (o/e) 0.54, 90% interval 0.4 to 0.74. The upper end of that interval is the gene's LOEUF score, 0.74, which puts it in group 3 of 6, group 1 being the genes least tolerant of losing a copy. Missense variants: 413 observed, 531.68 expected, observed/expected ratio (o/e) 0.78, 90% interval 0.72 to 0.84. Synonymous variants: 172 observed, 206.62 expected, observed/expected ratio (o/e) 0.83, 90% interval 0.73 to 0.94.
Homologues: Orthologues: chimpanzee FDPS (100% identical), macaque FDPS (97% identical), pig FDPS (88% identical), dog FDPS (87% identical), rat Fdps (85% identical), mouse Fdps (71% identical), guinea pig FDPS (71% identical), rabbit FDPS (71% identical), tropical clawed frog fdps (60% identical), zebrafish fdps (53% identical), Drosophila melanogaster Fpps (42% identical), Caenorhabditis elegans fdps-1 (29% identical).
Diseases named in the same sentence as FDPS in open-access papers:
FDPS is named in the same sentence as 84 diseases in open-access papers, as found by Europe PMC text mining. Sharing a sentence is not in itself a finding about the gene and the disease. The quoted sentences say what the papers report.
osteoporosis (22 papers, 2010 to 2024). A condition of reduced bone mass, with decreased cortical thickness and a decrease in the number and size of the trabeculae of cancellous bone (but normal chemical composition), resulting in increased fracture incidence. "In previous studies, the FDPS rs2297480 variant was associated with changes in the BMD of osteoporosis patients treated with bisphosphonates, where the AA genotype was associated with BMD gain while the CC with loss of BMD during treatment." (PMID 38891810, 2024). "Our study showed a strong association between osteoporosis and TT genotype of FDPS rs2297480, and with CC genotype of LRP5 rs3736228." (PMID 31774873, 2019). "In conclusion, the influence observed of FDPS expression and the rs2897480 variant on alendronate treatment highlights the importance of a genetic approach to improve the efficacy of treatment for primary osteoporosis." (PMID 38891810, 2024). "Women with TT genotype in FDPS rs2297480 had significantly lower bone mineral density values in the lumbar spine and total hip, and the presence of the T allele was significantly associated with the osteoporosis." (PMID 31774873, 2019). "This study aimed to assess the relationship between bone mineral density and genotypes of four polymorphisms in previously detected osteoporosis-candidate genes (FDPS rs2297480, LRP5 rs3736228, SOST rs1234612, VKORC1 rs9934438) in postmenopausal Romanian women with primary osteoporosis." (PMID 31774873, 2019). "Furthermore, to assess the impact of the variant on the mRNA expression of the FDPS gene, we analyzed its expression profile in relation to the therapeutic failure of alendronate sodium among a population-based sample of postmenopausal women with osteoporosis." (PMID 38891810, 2024). "Alendronate is used to treat osteoporosis, and it has been previously tested as an inhibitor of T. cruzi farnesyl diphosphate synthase, whereas flucytosine, an antifungal drug, has also not been tested against T. cruzi." (PMID 39202874, 2024). "At the same time, it is worth noting that in previously published studies the ambiguous results of the association of FDPS and GGPS1 gene variants with antiresorptive therapy of osteoporosis were obtained." (PMID 31437227, 2019). "Our study showed a strong association between bone mineral density and polymorphisms in the FDPS gene, and a borderline association with LRP5 and SOST polymorphisms in postmenopausal Romanian women with osteoporosis." (PMID 31774873, 2019). "For example, sodium alendronate, an osteoporosis treatment that targets farnesyl diphosphate synthase, has many of the residues involved in drug interaction conserved in three homologues identified by the pipeline." (PMID 30346968, 2018). "Additionally, we explored secondary and tertiary targets identified in this study and found that drugs targeting FDPS have been approved for the treatment of osteoporosis." (PMID 38707907, 2024). "In conclusion, we reported for the first time the importance of identified allelic combinations of SOST rs1234612, PTH rs7125774, FDPS rs2297480, and GGPS1 rs10925503 gene variants for evaluation of the individual resistance or sensitivity to BPs treatment of osteoporosis." (PMID 31437227, 2019). "The purpose of the present study is to evaluate the relation between BMD and genotypes of four SNPs in previously reported osteoporosis candidate-genes (FDPS rs2297480, LRP5 rs3736228, SOST rs1234612, VKORC1 rs9934438) in a cohort of postmenopausal Romanian women." (PMID 31774873, 2019). "Moreover, zoledronate and alendronate, which are FDA-approved FDPS inhibitors, have been widely used to treat osteoporosis." (PMID 30333528, 2018). "Aminobisphosphonates (NBPs) are the first-choice medication for osteoporosis (OP); NBP treatment aims at increasing bone mineral density (BMD) by inhibiting the activity of farnesyl diphosphate synthase (FDPS) enzyme in osteoclasts." (PMID 38891810, 2024).
osteoporosis (continued). "The downstream enzyme farnesyl diphosphate synthase (FDPS) is the target of the nitrogenous bisphosphonates including risedronate and zoledronate, which are widely used for treatment of osteoporosis." (PMID 25161722, 2014). "In addition to SmHMGR, there are a number of other enzymes downstream in the pathway that could be interrogated for development of an anti-parasite therapy based on clinical precedent in oncology (farnesyl transferase) and osteoporosis (farnesyl diphosphate synthase)." (PMID 24489942, 2014). "Our study’s findings align with this mechanism, as a higher expression of FDPS was noted in the osteoporosis non-responder (OP-NR) group." (PMID 38891810, 2024). "Administration of the bisphosphonates drugs which contain nitrogen (such as zoledronate), in patients of osteoporosis and hypercalcemiain malignancies, lead to enhanced intracellular IPP levels via inhibition of one of the mevalonate pathway enzymes i.e., farnesyl diphosphate synthase." (PMID 34092966, 2021).
glioblastoma (17 papers, 2015 to 2025). The most malignant astrocytic tumor (WHO grade IV). "FDPS mRNA in patients with glioblastoma was associated with malignancy in three independent microarray data sets." (PMID 30333528, 2018). "FDPS, a key enzyme in the mevalonate pathway, is overexpressed in various malignancies, including prostate cancer, glioblastoma, colon cancer, and pancreatic cancer." (PMID 40956822, 2025). "Among these differentially expressed genes, the isoprenoid biosynthesis enzyme farnesyl diphosphate synthase (FDPS) is critical for the survival of glioblastoma stem cells." (PMID 37653037, 2023). "FDFT1 is lowly expressed in some cancers; however, researchers found that farnesyl diphosphate synthase (FDPS), a key enzyme in isoprenoid biosynthesis, plays a crucial role in maintaining stemness in glioblastomas." (PMID 35391801, 2022). "These primary glioblastoma cells were positive for the expression of EGFRwt, p21waf, and FDPS compared to U343 glioma cell line and normal human astrocytes representing their healthy counterpart." (PMID 31993371, 2019). "FDPS mRNA levels are also upregulated in glioblastoma samples compared with normal samples in other microarray data sets." (PMID 30333528, 2018). "In this study, we determined that farnesyl diphosphate synthase (FDPS), a key enzyme in isoprenoid biosynthesis, plays an important role in maintaining glioblastoma stemness." (PMID 30333528, 2018). "In particular, farnesyl diphosphate synthase (FDPS), a key enzyme in isoprenoid biosynthesis, was found to play an important role in maintenance of glioblastoma stemness." (PMID 30333528, 2018). "Hyonchol Jang at the National Cancer Center in Goyang, South Korea and co-workers discovered that an enzyme called farnesyl diphosphate synthase (FDPS) helps maintain stemness in glioblastoma." (PMID 30333528, 2018). "On the other hand, FDPS inhibition has shown an increased paclitaxel-induced apoptotic cell death in U87 glioblastoma cells." (PMID 27145226, 2016). "Glioblastoma cells were apoptotic when FDPS was knocked down." (PMID 35391801, 2022). "In accordance with these findings, FDPS mRNA was significantly upregulated in glioblastoma cells compared with normal cells and in samples from patients who died within 3 years compared with samples from living patients in three independent microarray data sets." (PMID 30333528, 2018). "Knockdown of FDPS almost completely inhibited the formation of secondary TSs in patient-derived glioblastoma sphere cells, suggesting that FDPS is critical for the maintenance of glioblastoma sphere cells." (PMID 30333528, 2018). "We first checked whether the FDPS mRNA level was reflected by its protein level to confirm the role of FDPS in the formation of glioblastoma sphere cells." (PMID 30333528, 2018). "Glioblastoma, the most aggressive brain cancer, is highly dependent on the MVA pathway for the synthesis of lipid moieties critical for cell proliferation, and FDPS is a key intermediate enzyme in this pathway." (PMID 35328637, 2022). "GGPS1, FDPS, and GART are upregulated in multiple cancers in addition to breast cancer (also TNBC), including hard-to-treat cancers such as esophageal, pancreatic, lung, and oral cancers and glioblastoma." (PMID 33670680, 2021). "In this study, inhibiting FDPS but not FDFT1 significantly affected TS formation, suggesting that protein prenylation may be important for glioblastoma TS formation." (PMID 30333528, 2018).
glioma (13 papers, 2017 to 2026). A benign or malignant brain and spinal cord tumor that arises from glial cells (astrocytes, oligodendrocytes, ependymal cells). "Previous studies have shown that FDPS is significantly overexpressed in glioma tissues and is associated with poor prognosis, promoting tumor growth." (PMID 41523581, 2026). "To demonstrate whether the oncogenic roles of FDPS in glioma are macrophage‐dependent, we investigated the susceptibility of macrophages to liposomal clodronate treatment." (PMID 32596949, 2020). "In this study, FDPS expression correlates with the majority of gene signatures related to macrophages and are closely associated with macrophage density, suggesting the tumour‐promoting effects of FDPS in glioma might be linked to the macrophage infiltration." (PMID 32596949, 2020). "FDPS was confirmed to promote prostate cancer progression and glioma growth through modulation of small GTPases/AKT axis or regulating CCL20 via the Wnt/β-catenin signaling pathway." (PMID 37406019, 2023). "ATP-binding cassette transporter (ABCE1), being a chaperone, associates with chemotherapy resistance in glioma via PI3K/Akt/NF-κB pathway form PPIs with EBP and FDPS enzymes." (PMID 34440098, 2021). "FDPS was correlated with macrophage infiltration in glioma and pharmacological deletion of macrophages largely abrogated the oncogenic functions of FDPS in glioma." (PMID 32596949, 2020). "We also identified FDPS, which regulated the microenvironment of tumour and thus has a significant part in the tumour progression of glioma." (PMID 32596949, 2020). "In this study, we found that FDPS is overexpressed in glioma compared with corresponding normal tissues." (PMID 32596949, 2020). "An enzyme of mevalonate pathway, farnesyl diphosphate synthase (FDPS) is expressed at high levels in glioma and several other cancers." (PMID 32596949, 2020). "Kaplan‐Meier survival analysis showed that patients with glioma and overexpression of FDPS in their tumours exhibited decreased overall survival compared with those with low expression of FDPS in their tumours." (PMID 32596949, 2020). "In the current study, we evaluated the dysregulated FDPS expressed by glioma cells and uncover its oncogenic functions in glioma." (PMID 32596949, 2020). "We next assessed the oncogenic role of FDPS in glioma, by carrying out Western blotting to examine the expression of FDPS in NHAs cells and in other glioma cell lines (H4, U87, U118, U251 and A172)." (PMID 32596949, 2020). "Our results indicated that FDPS is up‐regulated in glioma tissues compared with normal tissues and that FDPS overexpression promotes glioma proliferation and TAMs recruitment by regulating CCL20." (PMID 32596949, 2020). "In line with this, we showed that deletion of macrophages by liposomal clodronate largely compromises the growth‐promoting effects of FDPS in syngeneic model, suggesting that the oncogenic roles of FDPS in glioma are largely dependent on macrophages." (PMID 32596949, 2020). "For several decades, mevalonate pathway enzymes (including FDPS) were examined for their role in cellular physiology, although, their role in various cancers including glioma remains elusive." (PMID 32596949, 2020). "Taken together, these results suggest that overexpression of FDPS was frequently detected in glioma." (PMID 32596949, 2020). "Lately, we found that GBM express altered levels of the FDPS protein, which abnormally accumulated in all glioma cell lines and in the tumor infiltrated brain of 34 patients." (PMID 31993371, 2019). "In conclusion, overexpressed FDPS exhibits an immunomodulatory role in glioma." (PMID 32596949, 2020). "The results showed that FDPS levels were elevated in tumour tissues compared with the corresponding adjacent non‐tumour tissues, with strong staining of FDPS detected in 60% of the glioma tissues." (PMID 32596949, 2020).
glioma (continued). "For more robust argument, we evaluated the level of the which mediates target gene activation, the active form of β‐catenin and observed significantly decrease in activated β‐catenin when FDPS was knocked down and elevated when FDPS in glioma cells, where it was ectopically expressed." (PMID 32596949, 2020). "Together, our results suggest that FDPS is a novel target for overcoming chemoresistance in glioma." (PMID 32596949, 2020). "While, knockdown FDPS suppressed migration and invasion in glioma U87 and U251 cells." (PMID 32596949, 2020). "FDPS protein levels in glioma cells were confirmed through Western blotting." (PMID 32596949, 2020). "Thus, FDPS exerts a significant role in glioma invasion and migration." (PMID 32596949, 2020). "This led us to explore the use of zoledronate, a bisphosphonate drug that inhibits farnesyl diphosphate synthase to accumulate DMAPP and IPP, or a BTN3A1 agonistic antibody 20.1 to sensitize WAT primary glioma cells to Vγ9Vδ2 T cell killing." (PMID 37770968, 2023). "To address this issue, we overexpressed FDPS in a mouse glioma cell line GL261, which showed faint FDPS protein expression." (PMID 32596949, 2020). "Therefore, targeting FDPS may be an effective therapeutic strategy for glioma." (PMID 32596949, 2020). "FDPS mRNA, protein and enzyme activity were analyzed in a cohort of stage III-IV glioma patients (N = 49) and primary derived cells." (PMID 29075041, 2017). "In the glioma cells, the EGFR signaling pathway was decreased via reduction of the STAT3, ERK, and AKT cascade, while iPA inhibited the farnesyl diphosphate synthase (FDPS) activity via reduction of protein prenylation, thus arresting the proliferation of thyroid cancer cells." (PMID 36551529, 2022). "We also observed that the overexpression of HMGCS1, GGPS1, FDPS, and GART in breast, ovarian, endometrial, pancreatic, and CNS cancers correlated well with a reduction in the overall survival of patients when compared with that of patients without overexpression of these genes." (PMID 33670680, 2021). "Genes in the mevalonate pathway (ACAT2, HMGCS1, and HMGCR) and downstream in the cholesterol biosynthetic pathway (FDPS, FDFT1, and SQLE), were all downregulated in dense NHAs but not dense glioma TS lines." (PMID 28118603, 2017).
prostate carcinoma (12 papers, 2015 to 2025). A carcinoma that arises from epithelial cells of the prostate gland. "Seshacharyulu P found that farnesyl-diphosphate synthase (FDPS) cooperated with PTEN loss to promote prostate cancer progression through modulation of small GTPases/AKT axis." (PMID 35200397, 2022). "In prostate cancer cells, FDPs enzyme intervention can also induce autophagy by inhibiting the production of GGPP, which is also related to the obstruction of the isoprene process of small G protein Rab6." (PMID 35397636, 2022). "Farnesyl diphosphate synthase (FDPS), a mevalonate pathway enzyme that synthesizes isoprenoids, plays an oncogenic role in PTEN-deficient prostate cancer progression." (PMID 33572160, 2021). "FDPS promotes prostate cancer progression, hinting at its potential unfavourable role in OSA." (PMID 38372422, 2024). "The noted upregulation of GGPS1 and FDPS is an important observation in the context of breast cancer pathogenesis as these enzymes are components of the mevalonate pathway with role in cholesterol biosynthesis and bone metastasis of breast cancer, prostate cancer, and multiple myeloma." (PMID 33670680, 2021). "Similarly, forced overexpression of FDPS in cancer cells resulted in activation of ERK and AKT pathways in prostate cancer." (PMID 34971971, 2022). "We found that the levels of GGPS1, FDPS, and GART were not upregulated in prostate cancer." (PMID 33670680, 2021).